BDNF (brain derived neurotrophic factor)
Diseases named in the same sentence as BDNF in open-access papers (continued):
Sharing a sentence is not in itself a finding about the gene and the disease.
schizophrenia (continued). "The association between depressive symptoms and BDNF in patients with schizophrenia has received limited research attention, despite the fact that many studies have investigated the associations between BDNF and memory and cognitive performance in schizophrenia." (PMID 35757201, 2022). "Indeed we have previously used a chronic METH treatment protocol in mouse models of schizophrenia risk factors, such as reelin and brain-derived neurotrophic factor (BDNF)." (PMID 36358429, 2022). "At present, there is no consistent conclusion on whether the rs11030101, rs2030324, and rs6265 loci of the BDNF gene are susceptibility genes for schizophrenia." (PMID 35368680, 2022). "BDNF Val66Met polymorphism has been associated with impaired memory function, vulnerability to stress, stress-related disorders, and cognitive/affective deficits in other psychiatric disorders such as schizophrenia." (PMID 35145065, 2022). "Generally speaking, as an important susceptibility gene for fever in schizophrenic patients, polymorphisms of the BDNF gene may be related to the susceptibility to schizophrenia and the severity of symptoms." (PMID 35368680, 2022). "Moreover, BDNF is associated with various degenerative diseases and is shown to be upregulated in chronic stress, including ischemia injury or schizophrenia." (PMID 35458486, 2022). "In this mini-review, we will summarize evidence for the dysfunctions in dysbindin-1 (DTNBP1), a protein coding gene regularly implicated in schizophrenia as well as brain-derived neurotrophic factor (BDNF), and GABAergic circuit function in relation to schizophrenia." (PMID 35815020, 2022). "Decreased BDNF expression has been associated with schizophrenia." (PMID 35444632, 2022). "Furthermore, the alterations of the miR-30a family in the prefrontal cortex of patients with schizophrenia are associated with changes in BDNF levels." (PMID 35916975, 2022). "BDNF could serve as a potential diagnostic and prognostic biomarker, which may allow us to detect schizophrenia early and track treatment response." (PMID 35447946, 2022). "Notably, we also detected a novel, Bonferroni significant association with BDNF upon meta-analysis of schizophrenia with alcohol dependence and cannabis use disorder." (PMID 36151087, 2022). "As statistically significant associations between Met of BDNF gene and a1-PI and the degree of frontal dysfunction were demonstrated, these parameters can serve as markers for assessing the severity of frontal lobe damage in schizophrenia patients." (PMID 34025476, 2021). "Furthermore, SNX25 recent ascribed role in TrkB degradation and BDNF-TrkB signaling suggests additional associations with epilepsy and also with schizophrenia, attending on BDNF and TrkB-signaling molecules on the pathophysiology of these conditions." (PMID 33931804, 2021). "The results showed that the age of onset and cognitive function of the schizophrenia patients was related to changes in clinical characteristics, with serum BDNF levels and BDNF Val66met polymorphisms influencing the age of onset of schizophrenia, cognitive function and clinical symptoms." (PMID 35194435, 2021). "Although the relationship between changes in the brain and serum BDNF levels due to BDNF expression is not fully understood, it is thought that a genetic predisposition towards schizophrenia may affect BDNF levels." (PMID 34763683, 2021). "In addition, studies have shown that BDNF is associated with the development of neurodevelopmental disorders, such as schizophrenia and Attention‐Deficit/Hyperactivity Disorder (ADHD)." (PMID 32869548, 2020). "Given BDNF’s protective role in the developing brain, it is possible that downregulation of BDNF could exacerbate schizophrenia risk in the perinatal window." (PMID 32719625, 2020).
schizophrenia (continued). "The function of BDNF in a pathophysiological framework such as schizophrenia though should be met with caution, as for example, genome wide association studies in schizophrenia have shown variants in multiple genes regulating neuronal and synaptic plasticity and dendritic growth." (PMID 32153434, 2020). "Furthermore, our prior study showed that CSF, a neuroplasticity-associated protein BDNF ‘pro-peptide’-level change, was also downward in patients with schizophrenia and those with MDD28." (PMID 32439851, 2020). "Mattson and Mennerick are of the opinion that the lack of structured rehabilitation intensifies negative symptoms and causes a decrease in the neurotrophic factor BDNF levels, which, in turn, results in poorer cognitive and social functioning of patients diagnosed with schizophrenia." (PMID 32517043, 2020). "The encoding BDNF gene, located on chromosome 11, has beenwell-reported to be correlated with substance abuses and psychiatric diseases, suchas nicotine dependence, alcohol dependence, schizophrenia, personality, and attention deficit hyperactivity disorder." (PMID 31787753, 2020). "We found that the ATAAT haplotype (built with five SNPs in the TrkB gene) was associated with a lower risk of schizophrenia for men but that the GTAGCG haplotype (build with five of the analysed SNPs TrkB and rs6265 BDNF SNP) was connected with a lower risk of schizophrenia for women." (PMID 32351633, 2020). "As BDNF regulates axonal and dendritic growth, altered BDNF levels in schizophrenia patients might underlie changes in structural connectivity that have been identified by magnetic resonance imaging (MRI)." (PMID 32153434, 2020). "BDNF is relevant for schizophrenia-related phenotypes, and disruption of BDNF signaling is associated with altered synaptic plasticity and neurodevelopment of schizophrenia." (PMID 32973585, 2020). "It is possible that the increase in BDNF levels observed in the placebo group reflects the early stage of the disease, where the processes related to the BDNF pathway are more active and susceptible to change than in chronic schizophrenia patients." (PMID 31098654, 2019). "It is hypothesized that yoga will improve psychopathology and emotion processing, increase serum brain derived neurotrophic factor (BDNF) and plasma oxytocin levels and effect changes in cerebral activation in areas of the brain associated with schizophrenia." (PMID 31651843, 2019). "Similarly, upregulated MMP-9 serum levels were found to be strongly associated with levels of mature BDNF (MMP-9 aids in the formation of mature BDNF from pro-BDNF) in schizophrenia patients." (PMID 31172215, 2019). "Importantly, these rhythms drive differential expression patterns of these and several other genes that have long been implicated in schizophrenia (including BDNF and GABAergic-related transcripts)." (PMID 31399567, 2019). "We utilized a heterozygous, conditional knockout of Bdnf on allele using the Cre/loxP system, as BDNF is reduced in participants with schizophrenia, and increasing protein levels may have beneficial clinical outcomes." (PMID 31185023, 2019). "Another study explored the impact of the BDNF Val66Met gene variant in schizophrenia." (PMID 31105606, 2019). "Downregulation of BDNF has also been associated with increased DNA methyltransferase (DNMT) binding to BDNF promoters in glutamatergic neurons of schizophrenia-affected individuals, highlighting the importance of epigenetic mechanisms in the regulation of this pathway." (PMID 31777665, 2019). "Sex-specific associations of the BDNF Val66Met polymorphism with cortisol responses to mental stress, neurocognitive function in schizophrenia, sympathetic tone, HPA axis reactivity to psychological stress, and attention-deficit/hyperactivity disorder (ADHD) have also been reported." (PMID 29867348, 2018).
schizophrenia (continued). "Brain-derived neurotrophic factor may play a role in schizophrenia etiology, but whether BDNF plays a causative or merely incidental role remains unknown." (PMID 30618607, 2018). "There is convincing evidence of an association between BDNF and schizophrenia." (PMID 28358316, 2017). "NTRK2 together with BDNF is associated with paranoid schizophrenia." (PMID 30090857, 2017). "Of these BDNF gene polymorphisms, the G196A and C270T SNPs were significantly associated with this diseases in some studies, especially C270T polymorphism was susceptibility to East Asian schizophrenia and AD." (PMID 28539884, 2017). "Association studies have further suggested that BDNF could be involved in both susceptibility to schizophrenia and in clinical symptom severity." (PMID 29321734, 2017). "BDNF Val66Met polymorphism is associated with aggressive behavior in schizophrenia." (PMID 29472953, 2017). "Low expression of NGF in prefrontal cortex and low levels of BDNF in hippocampus, measured in rodent models of schizophrenia, may indicate that they are associated with cognitive impairment during disease progress and its therapy with antipsychotic drugs." (PMID 28881851, 2017). "Another genetic BDNF marker, dinucleotide microsatellite repeat polymorphism (GT)n, was associated with treatment response and chlorpromazine-induced extrapyramidal reverse effects in Chinese patients with schizophrenia." (PMID 28358316, 2017). "Finally, BDNF is considered to be an important factor underlying the pathophysiology of schizophrenia." (PMID 27524962, 2016). "Our results provide new evidences suggesting a link between Perspective Taking and the BDNF Val66Met polymorphism, which may partly explain why schizophrenia was associated independently with Perspective Taking and the BDNF Val66Met polymorphism." (PMID 26901829, 2016). "It has previously been proposed that alterations in inhibitory circuits potentially driven by deficits in BDNF/TrkB signaling could underlie the etiology of schizophrenia." (PMID 25762898, 2015). "Importantly, both BDNF gene variants and miR-26a expression have been implicated in the vulnerability and onset of schizophrenia, alcohol abuse and mood disorders in both human patients and rodent models." (PMID 24416161, 2014). "Because cognitive dysfunction is associated with schizophrenia, we hypothesized that the serum BDNF levels are associated with the IGT scores of the chronic schizophrenia patients." (PMID 25538582, 2014). "There has been extensive research over the past decade examining the influence of the val66met single nucleotide polymorphism (SNP) of the BDNF gene and its association with psychiatric conditions including schizophrenia, anorexia nervosa, and obsessive-compulsive disorder." (PMID 24672724, 2014). "Studies of the BDNF Val66Met (rs6265) showed that the Met allele is associated with lower levels of BDNF secretion and with abnormal hippocampal structure and function, providing evidence for the direct involvement of BDNF in schizophrenia." (PMID 25538582, 2014). "Finally, based on associations between the Val66Met polymorphism and OCS in schizophrenia, the brain derived neurotrophic factor (BDNF) has recently been proposed as a forth candidate gene." (PMID 26556409, 2014). "In conclusion, both depressive symptoms and the serum BDNF levels may be associated with the impairment of decision-making in schizophrenia patients." (PMID 25538582, 2014). "An understanding of the regional, laminar and diagnostic specificities of BDNF and trkB−TK+ deficits in schizophrenia and mood disorders may provide a guide for future therapeutic strategies aimed at this system." (PMID 24802307, 2014). "In the present study, we recruited 402 patients with paranoid schizophrenia and 406 control subjects to examine the putative association between paranoid schizophrenia and polymorphisms in BDNF (rs6265) and NTRK2 genes (rs1387923, rs2769605, and rs1565445) in a Chinese Han population." (PMID 24069289, 2013).
schizophrenia (continued). "Thus, more and more research was carried out to explore the role of BDNF functional polymorphism rs6265 in development of schizophrenia." (PMID 24069289, 2013). "We hypothesized that schizophrenia patients with FRS will show deficient BDNF level in comparison with healthy controls while those without FRS will not differ significantly." (PMID 23847552, 2013). "The aim of the present study was to investigate whether a BDNF deficit would modulate effects of chronic cannabis intake, a well-described risk factor for schizophrenia development." (PMID 24155701, 2013). "However, they analyzed their data in combination with results from other studies and conducted a meta-analysis, in which they found that both the T allele of BDNF 270 and the homozygous state for Val66Met are associated with the presence of schizophrenia." (PMID 23785335, 2013). "All these evidence suggest that dysfunction of BDNF and TrkB may be involved in the pathophysiology underlying schizophrenia." (PMID 24069289, 2013). "In patients with schizophrenia, a deficiency in BDNF signaling mediated by the receptor TrkB may result in a reduction of the synthesis of GABA in the dorsolateral prefrontal cortex." (PMID 23785335, 2013). "One study found an association between maintained increases in serum BDNF levels and improved cognition in patients with schizophrenia, and suggested that serum BDNF levels could be used as a biological marker of cognitive improvement." (PMID 23320462, 2013). "BDNF, the most widely distributed neurotrophin in the central nervous system, is highly expressed in brain regions that are critically implicated in the pathogenesis of schizophrenia – the prefrontal cortex and hippocampus." (PMID 23847552, 2013). "BDNF is associated with psychiatric diseases such as depression or schizophrenia." (PMID 22269819, 2012). "COMT Val158Met and BDNF Val66Met polymorphisms have long been identified as candidate genes for schizophrenia, but recent meta-analyses and large-scale genome-wide association studies of schizophrenia and bipolar disorder have failed to confirm their direct role in the etiology of these diseases." (PMID 24278715, 2012). "Dysregulation would cause information overwriting, which might be a clue to why schizophrenia has been related to BDNF reduction." (PMID 19183490, 2009). "The present study investigated whether Sprouty2, a regulator of growth factor signaling, is abnormally expressed in schizophrenia, and is associated with the changes in BDNF mRNA in this disorder." (PMID 18335055, 2008). "Furthermore, similar to schizophrenia, BDNF Val66Met has been implicated in MDD." (PMID 41254423, 2025). "Additionally, our data may provide a functional link between MMP-9, BDNF and their involvement in many brain pathologies, which has previously been implicated, for example, in addiction, schizophrenia, ischemic stroke, or even cochlear implantation." (PMID 40991708, 2025). "Additionally, the BDNF Val66Met polymorphism has been implicated in schizophrenia." (PMID 41254423, 2025). "An analysis of postmortem brains from schizophrenia patients revealed elevated levels of 5mC and 5hmC in the BDNF-regulatory regions in the frontal cortex and hippocampus, including the promoter regions, suggesting a strong association between BDNF methylation and schizophrenia." (PMID 38203806, 2024). "In addition, it has been found that the presence of the Met allele in the Val66Met polymorphism of the BDNF gene may be associated with the risk of attempted suicide in patients with schizophrenia." (PMID 38680078, 2024). "Furthermore, schizophrenia patients with the same genotype and alleles exhibited different symptoms, which may be related to the differences in BDNF expression levels." (PMID 38203806, 2024). "Thus, BDNF gene variations could represent a risk factor for weight escalation in the male schizophrenia population." (PMID 38988887, 2024).
schizophrenia (continued). "The aim of this systematic review and meta-analysis was to determine whether the use of ECT is associated with a change in the concentration of BDNF in patients diagnosed with treatment-resistant schizophrenia compared to the concentration of this factor in patients treated with antipsychotics only." (PMID 37685795, 2023). "Moreover, the hypothesis proposed that allele A of BDNF rs6265 confer a protection for schizophrenia." (PMID 36325525, 2022). "In addition, more and more evidence shows that BDNF rs6265 changes the clinical manifestation and genetic risk structure of schizophrenia, which may be achieved by affecting the clinical manifestation and treatment response." (PMID 36325525, 2022). "Thus, BDNF, the most prevalent growth factor in the central nervous system, serves as a potential marker for psychiatric diseases and mental illnesses and is widely implicated in schizophrenia, major depressive disorder (MDD), and bipolar disorder." (PMID 36742047, 2022). "A meta-analysis of population-based, case-control studies on BDNF Val66Met, which considered the dominant ethnicity Caucasian or Asian, suggested that the 66Met allele acted as a protective effect for substance-related disorders and exerted a risk factor for eating disorders and schizophrenia." (PMID 35815047, 2022). "Similarly, BDNF-Val66Met-polymorphism may interact with tDCS to predict cortical plasticity in patients with schizophrenia." (PMID 34069556, 2021). "Thus, it is unknown whether obesity could have a direct impact on symptoms of schizophrenia, or whether it is merely a side-effect of treatment or an associated morbidity with shared pathophysiological aspects, like BDNF alterations and inflammation." (PMID 32226399, 2020). "Additionally, the BDNF pathway may be relatively inhibited from chronically elevated cortisol, further promoting hippocampal injury and schizophrenia risk." (PMID 32719625, 2020). "In addition, some studies suggest that baseline BDNF levels in schizophrenia patients might reflect the susceptibility towards available drug therapies." (PMID 30117106, 2019). "Furthermore, the polymorphisms of BDNF were reported to be associated with schizophrenia." (PMID 30233327, 2018). "Finally, the severity of schizophrenia symptoms is associated with abnormal serum levels of several glutamate transmission related factors, including brain-derived neurotrophic factor (BDNF), vascular endothelial growth factor (VEGF), D-serine, G72, and multiple inflammatory factors." (PMID 30459650, 2018). "Therefore, future preclinical and clinical studies may significantly clarify the association between DARPP-32, BDNF and other genes polymorphism to elucidate the mechanisms of these genetic associations with schizophrenia illness in human brain." (PMID 28881851, 2017). "However, it was also reported that the BDNF Val allele could be related to lower hippocampal volume and be one of the genetic risk factors for schizophrenia." (PMID 28358316, 2017). "Brain-derived neurotrophic factor (BDNF) and its receptor TrkB are known to play a role in the maturation of inhibition during post-natal life and deficits in these factors are linked to multiple late-onset psychiatric disorders, including schizophrenia and mood disorders." (PMID 25762898, 2015). "However, the BDNF Val66Met polymorphism has been associated with increased schizophrenia risk." (PMID 25762938, 2015). "However, genetic associations between BDNF and schizophrenia had a contradicting result." (PMID 24069289, 2013). "Therefore, BDNF variants may be among several factors affecting progressive brain volume changes in schizophrenia." (PMID 23785335, 2013). "Specifically, studies have reported that the BDNF Met allele carriers (i.e., Val/Met, Met/Met) of the BDNF demonstrated poorer verbal memory, processing speed, and general intelligence in controls and individuals with various neuropsychiatric conditions (e.g., schizophrenia)." (PMID 23087644, 2012).